HEXA (hexosaminidase subunit alpha)
Description:
Hydrolyzes the non-reducing end N-acetyl-D-hexosamine and/or sulfated N-acetyl-D-hexosamine of glycoconjugates, such as the oligosaccharide moieties from proteins and neutral glycolipids, or from certain mucopolysaccharides. The isozyme S is as active as the isozyme A on the anionic bis-sulfated glycans, the chondroitin-6-sulfate trisaccharide (C6S-3), and the dermatan sulfate pentasaccharide, and the sulfated glycosphingolipid SM2. The isozyme B does not hydrolyze each of these substrates, however hydrolyzes efficiently neutral oligosaccharide. Only the isozyme A is responsible for the degradation of GM2 gangliosides in the presence of GM2A.
Synonyms: TSD
Tractability: Small molecule: a structure with a bound ligand is known; a high-quality ligand is known. Antibody: UniProt predicts a signal peptide or a membrane-spanning region. PROTAC: ubiquitination databases record sites on it; its protein half-life has been measured; a small molecule that binds it is known.
Target class: Enzyme; Hydrolase
Gene: Protein-coding gene on chromosome 15 (72,340,924 to 72,376,420, reverse strand). Ensembl gene ENSG00000213614.
Subcellular location: Lysosome
Subcellular location (Human Protein Atlas): Vesicles; Cytosol
Pathways (Reactome):
Metabolism: CS/DS degradation; Glycosphingolipid catabolism; Hyaluronan degradation; Keratan sulfate degradation
Disease: Defective HEXA causes GM2G1 (Hyaluronan metabolism)
Gene Ontology:
Molecular function: acetylglucosaminyltransferase activity; beta-N-acetylhexosaminidase activity; protein binding; protein heterodimerization activity; hydrolase activity, hydrolyzing O-glycosyl compounds
Biological process: ganglioside catabolic process; glycosaminoglycan biosynthetic process; glycosaminoglycan metabolic process; carbohydrate derivative metabolic process; carbohydrate metabolic process; dermatan sulfate proteoglycan catabolic process; hyaluronan catabolic process; lipid catabolic process
Cellular component: azurophil granule; beta-N-acetylhexosaminidase complex; extracellular exosome; extracellular region; membrane; endolysosome lumen; lysosomal lumen; lysosome
Genetic constraint (gnomAD): Loss-of-function variants: 42 observed, 57.38 expected, observed/expected ratio (o/e) 0.73, 90% interval 0.57 to 0.95. The upper end of that interval is the gene's LOEUF score, 0.95, which puts it in group 4 of 6, group 1 being the genes least tolerant of losing a copy. Missense variants: 551 observed, 581.15 expected, observed/expected ratio (o/e) 0.95, 90% interval 0.88 to 1.02. Synonymous variants: 195 observed, 227.21 expected, observed/expected ratio (o/e) 0.86, 90% interval 0.76 to 0.97.
Gene-disease validity (ClinGen):
ClinGen rates the evidence that HEXA causes each of these diseases.
Tay-Sachs disease (autosomal recessive): Definitive. GM2 gangliosidosis, variant B or Tay-Sachs disease is marked by accumulation of G2 gangliosides due to hexosaminidase A deficiency.
Homologues: Orthologues: chimpanzee HEXA (97% identical), macaque HEXA (95% identical), rabbit HEXA (87% identical), mouse Hexa (84% identical), pig HEXA (84% identical), rat Hexa (83% identical), dog HEXA (82% identical), guinea pig HEXA (78% identical), zebrafish hexa (55% identical), Caenorhabditis elegans hex-1 (39% identical), Drosophila melanogaster Hexo2 (35% identical), Drosophila melanogaster Hexo1 (32% identical), and 1 more. Paralogues in human: HEXB (56% identical).
Diseases named in the same sentence as HEXA in open-access papers:
HEXA is named in the same sentence as 93 diseases in open-access papers, as found by Europe PMC text mining. Sharing a sentence is not in itself a finding about the gene and the disease. The quoted sentences say what the papers report.
Tay-Sachs disease (63 papers, 2006 to 2026). "The first family presented a missense COL4A6 variant (NM_033641.4: c.1480G>A p.(Gly494Arg)), accounting for hearing loss, while a likely pathogenic HEXA variant (NM_000520.6: c.902T>G p.(Met301Arg)) explained Tay-Sachs disease features." (PMID 41092388, 2026). "Tay-Sachs disease is a lysosomal storage disorder caused by mutations in the HEXA gene, which encodes the α-subunit of β-hexosaminidase A-an enzyme that breaks down GM2 ganglioside." (PMID 41739308, 2026). "Mutations in either the HEXA or HEXB gene cause the GM2 gangliosidoses Tay-Sachs disease (TSD) or Sandhoff disease (SD), respectively." (PMID 39752451, 2025). "Gene therapy for infantile Tay-Sachs disease has involved the use of 2 monocistronic AAV vectors separately encoding the HEXA and HEXB genes." (PMID 40526437, 2025). "The GM2 gangliosidoses, Tay-Sachs disease and Sandhoff disease, are devastating neurodegenerative disorders caused by β-hexosaminidase A (HexA) deficiency." (PMID 39752451, 2025). "Tay-Sachs disease is a rare autosomal recessive lysosomal storage disorder resulting from mutations in the HEXA gene." (PMID 40526437, 2025). "Biallelic mutations in HEXA, which encodes the α subunit, cause Tay-Sachs disease (TSD); biallelic mutations in HEXB, which encodes the β subunit, cause Sandhoff disease (SD)." (PMID 39276676, 2024). "We also evaluated PE6a and PE6b in HEK293T cells harboring the HEXA 1278insTATC mutation that causes Tay-Sachs disease." (PMID 37657419, 2023). "Tay-Sachs disease is a lethal lysosomal storage disorder caused by mutations in the HexA gene encoding the α subunit of the lysosomal β-hexosaminidase enzyme (HEXA)." (PMID 36928510, 2023). "Such attempt follows the successful model of population-based screening for the founder HEXA variants associated with Tay-Sachs disease in the Ashkenazi Jewish population, which has successfully reduced its incidence by 90%." (PMID 37670342, 2023). "HEXA - a homozygous variant in exon 7 (c.788C>T) causing Tay-Sachs disease, an autosomal recessive disorder." (PMID 37519562, 2023). "The late-onset form of Tay-Sachs disease displays when the activity levels of human β-hexosaminidase A (HexA) fall below 10% of normal, due to mutations that destabilise the native folded form of the enzyme and impair its trafficking to the lysosome." (PMID 35575117, 2022). "The top 2 significant human comorbid diseases for Influenza A virus (flu) were Tay-Sachs disease (mutations in HEXA) and Sandhoff disease (mutations in HEXB) that are very similar rare genetic diseases." (PMID 36463386, 2022). "Tay-Sachs disease is characterized by reduced hexosaminidase A (Hex A) enzyme activity as a result of missense mutations in the HEXA gene." (PMID 35242840, 2022). "We demonstrated the utility of the double tap method by installing two disease-relevant mutations (an A to T point mutation in the HBB gene that causes sickle cell disease, and a 4-bp insertion in the HEXA gene that causes Tay-Sachs disease)." (PMID 35534455, 2022). "They increased the levels of lysosomal HexA activity in Tay-Sachs patient fibroblasts having the G269S mutation, the highest prevalent in late-onset Tay-Sachs disease." (PMID 35575117, 2022). "It is essential for the degradation of GM2 by HEXA, and loss-of-function mutation results in a highly similar clinical presentation to Tay-Sachs disease." (PMID 36131294, 2022). "Mutations in HEXA cause Tay-Sachs disease in humans, which is a neurological disorder characterized by an accumulation of GM2 gangliosides in neurons." (PMID 33572113, 2021). "A well-characterized glycoside hydrolase in humans is HEXA, which localizes to the lysosome and is associated with Tay-Sachs disease." (PMID 34291044, 2021). "Tay-Sachs disease (TSD) is a progressive neurodegenerative disorder that occurs due to a deficiency of a β hexosaminidase A (HexA) enzyme, resulting in the accumulation of GM2 gangliosides." (PMID 34685379, 2021).
Tay-Sachs disease (continued). "HEXA activity is linked to autophagy and mutations in HEXA cause the lysosomal storage disorder Tay-Sachs disease." (PMID 34291044, 2021). "Mutations in HEXA cause Tay-Sachs disease, while mutations in CTSD are associated with breast cancer, Alzheimer’s disease, Parkinson’s disease, and a subtype of NCL called CLN10 disease." (PMID 33572113, 2021). "The current study revealed the structure and distribution of a large deletion mutation consisting of exons 6–10 of HEXA in Tay-Sachs disease." (PMID 31428437, 2018). "At the development stage there are methods of Tay-Sachs disease gene therapy using adeno- or adeno-associated viruses as vectors for the delivery of cDNA encoding α and β HexA subunit genes." (PMID 30524313, 2018). "GLB1 mutations in GM1 gangliosidosis, HEXA mutations in Tay-Sachs disease, and HEXB mutations in Sandhoff disease were found in all, of which GLB1 c.622C>T (p.R208C) in P108 was a common mutation for patients with GM1 gangliosidosis." (PMID 29451896, 2018). "The same study failed to prove association between PD and founder mutations in the lysosomal enzyme genes HEXA (Tay-Sachs disease) and MCOLN1 (mucolipidosis type IV)." (PMID 24386122, 2013). "Tay-Sachs disease is a severe lysosomal disorder caused by mutations in the HexA gene coding for the α-subunit of lysosomal β-hexosaminidase A, which converts GM2 to GM3 ganglioside." (PMID 20862357, 2010). "Tay-Sachs disease is a devastating neurodegenerative disorder that occurs early in childhood due to accumulation of GM2 gangliosides in neurons as a result of HEXA protein deficiency." (PMID 17144924, 2006). "GM2 gangliosidosis is lysosomal storage disorder caused by deficiency of the heterodimeric enzyme β-hexosaminidase A. Tay-Sachs disease is caused by variants in HEXA encoding the α-subunit and Sandhoff disease is caused by variants in HEXB encoding the β-subunit." (PMID 39802759, 2024). "On analysis of 15 cases, only a single case could be resolved whereby the case was enzymatically diagnosed to have Tay-Sachs disease and a single heterozygous variant c.902T>G in the HEXA gene was previously detected with the smMIP based assay." (PMID 38730490, 2024). "Tay-Sachs disease is an autosomal recessive disease caused by HEXA mutations." (PMID 35865957, 2022). "Indeed, our group has previously identified a common variant p.E462V in the HEXA gene in Tay Sach disease patients of Gujarati Indian ethnicity." (PMID 35729508, 2022). "Sandhoff disease is caused by mutations in the HEXB gene that encodes the β-subunit of either the β-hexosaminidase (HEXB: two β-subunits) or α-hexosaminidase (HEXA: one β- and one α-subunit) enzyme, while Tay-Sachs disease involves mutations in HEXA, which encodes the α-subunit of HEXA." (PMID 32435656, 2020). "Hypomyelination was reported in several LSDs, including GM1 gangliosidosis with deficiency in acid β-galactosidase due to GLB1 mutations, and GM2 gangliosidosis with deficiency in β-hexosaminidase A (Tay-Sachs disease, HEXA mutations) or β-hexosaminidases A and B (Sandhoff disease, HEXB mutations)." (PMID 29451896, 2018). "Mutations in the HEXA gene encoding the α-chain of (β-hexosaminidase-A) Hex-A leads to Tay-Sachs disease or B variant, while mutations in the β-chain encompassing HEXB gene leads to deficiency of both Hex-A and Hex-B (total-Hex) causing Sandhoff disease or O variant." (PMID 27402091, 2016). "Late Onset Tay- Sachs disease (LOTS) is a rare neurodegenerative lysosomal storage disease which results from mutations in the gene encoding the α subunit (HEXA) of β-hexosaminidase enzyme (HexA)." (PMID 25896637, 2015).
Tay-Sachs disease (continued). "Tay Sachs disease (TSD) (MIM# 272800) is an autosomal recessive neurodegenerative disorder due to β-hexosaminidase A deficiency caused by mutation in the HEXA gene (MIM* 606869) encoding the α subunit of hexosaminidase A, a lysosomal enzyme composed of α and β polypeptides." (PMID 22723944, 2012). "In the current work, we assessed whether Neu4 is the enzyme responsible in vivo for the metabolic bypass of the HexA defect in the mouse model of Tay-Sachs disease by studying mice with a double deficiency of Neu4 and HexA." (PMID 20862357, 2010). "Tay-Sachs disease (TSD) and Sandhoff disease are fatal neurodegenerative diseases without an effective therapy that are caused by mutations in the HEXA and HEXB genes, respectively." (PMID 41026525, 2025). "Tay-Sachs disease (TSD) is a rare lysosomal storage disorder (LSD) that results from loss-of-function mutations in gene HEXA, which code for the α-subunits of the heterodimeric enzyme β-Hexosaminidase A (Hexa)." (PMID 40019557, 2025). "Similarly, in Tay-Sachs disease, a lysosomal storage diseases caused by the loss of function of the enzyme β-hexosaminidase A (HEXA), it has been reported that the alpha-chain precursor of hexosaminidase is glycosylated normally but not phosphorylated in the Golgi." (PMID 38721528, 2024). "Tay-Sachs disease (TSD) is a rare neurodegenerative disorder caused by autosomal recessive mutations in the HEXA gene on chromosome 15 that encodes β-hexosaminidase." (PMID 30220252, 2018). "Tay-Sachs disease (TSD) is a neurodegenerative lysosomal disorder with an autosomal recessive inheritance caused by β-hexosaminidase α-subunit (HEXA) mutations." (PMID 25143775, 2014). "Here, we assess the effect of recombinant HexA and HexD3, a newly engineered mimetic of HexA optimized for the treatment of Tay-Sachs disease and Sandhoff disease." (PMID 39752451, 2025). "Mutations in the genes encoding the α- (HEXA) and β-subunits (HEXB), or GM2A (GM2A) lead to Tay-Sachs Disease (TSD; OMIM #272800), Sandhoff Disease (SD; OMIM #268800) and AB-Variant GM2 gangliosidosis (ABGM2; OMIM #272750), respectively." (PMID 38098938, 2023). "These genes include HEXA (Tay-Sachs disease), CDKN1B (Neoplasia), GATA1 (Thrombocytopenia, Thalassemia), and SH2D1A (Lymphoproliferative syndrome)." (PMID 38033082, 2023). "Tay-Sachs disease has been described in North American and British Jacob sheep that have a single base substitution in exon 11 of the HEXA gene, resulting in skipping of exon 11 and diminished Hex A activity." (PMID 35242840, 2022). "Three clinically similar subtypes of GM2 exist: Tay-Sachs disease (TSD), Sandhoff disease (SD), and GM2 activator deficiency, which result from mutation of HEXA, HEXB, and GM2A genes, respectively." (PMID 34456684, 2021). "β-hexosaminidase (Hex) is an important enzyme system in human body, encoded by two genes, HEXA and HEXB, are closely related to central nervous system (CNS) diseases such as Sandhoff disease (SD) and Tay-Sachs disease (TSD)." (PMID 34422641, 2021). "Effectiveness of this approach is evaluated in α or β HexA subunit defective model mice or Jacob sheep, in which Tay-Sachs disease arises spontaneously and is characterized by the same pathological features as in humans." (PMID 30524313, 2018). "Tay-Sachs disease (TSD) is a sphingolipid storage disorder caused by mutations in the HEXA gene." (PMID 29973161, 2018). "Tay-Sachs disease (TSD; MIM 272800), associated with mutations in HEXA, is a neurodegenerative disease caused by accumulation of GM2-ganglioside." (PMID 27362553, 2016). "Background and Aims: Carrier screening for Tay-Sachs disease is performed by sequence analysis of the HEXA gene and/or hexosaminidase A enzymatic activity testing." (PMID 27362553, 2016). "Tay-Sachs disease evolves due to accumulation of GM2 in neural cells in the central nervous system secondary to decreased HexA activity." (PMID 25896637, 2015).
Tay-Sachs disease (continued). "Late Onset Tay Sachs disease (LOTS) is a rare variant of Tay Sachs disease (TSD), that results from mutations in the gene encoding the α subunit of β-hexosaminidase A (HexA)." (PMID 25896637, 2015). "Our data suggest that the Neu4 depletion exacerbates the disease in HexA knockout mice, supporting the view that Neu4 is one of the modifier genes in the mouse model of Tay-Sachs disease." (PMID 20862357, 2010). "Hexosaminidases, such as HEXA and HEXB, are essential for the breakdown of glycolipids, and their mislocalization may disrupt normal cellular processes and cause Tay-Sachs disease." (PMID 38721528, 2024). "Tay-Sachs disease (TSD) is one of the lysosomal storage diseases (LSD) caused by a mutation in the HexA gene, encoding for the α subunit of lysosomal β-hexosaminidase A (HEXA), responsible for the degradation of GM2 to GM3 ganglioside." (PMID 36928510, 2023). "For instance, a 19-fold enriched frameshift indel, p.Tyr427IlefsTer5, in HEXA, contributes a 361-fold enrichment in genetic risk in AJ to non-AJ population to Tay-Sachs disease." (PMID 29795570, 2018). "Finally, we performed a limited carrier screening assessment, identifying 28 (4.6%) parents as carriers of P/LP variation in HBB (sickle cell anemia MIM:603903), HEXA (Tay-Sachs disease MIM:272800), or CFTR (cystic fibrosis MIM:219700)." (PMID 28554332, 2017). "First, reported in Ashkenazi Jews, who harbor a widespread missense HEXA mutation, p.Gly269Ser, late-onset Tay-Sachs disease occurs in non-Jews, and p.Gly269Ser is also found; other HEXA variants occur and should be sought given that expressivity in affected pedigrees in variable." (PMID 33005626, 2020). "The same principle applies to Tay-Sachs disease (TSD) research; HEXA−/− mice exhibit the characteristic reduction in β-hexosaminidase activity and accumulation of GM2 ganglioside but display almost no neurological symptoms." (PMID 41155400, 2025). "Three LSDs associated with GM2-gangliosidosis are Tay-Sachs disease (TSD, OMIM #272800), Sandhoff’s disease (SD, OMIM #268800), and GM2 activator protein deficiency (also called AB variant, OMIM #272750), and are associated with pathogenic variants in HEXA, HEXB, and GM2A, respectively." (PMID 35865957, 2022). "Tay-Sachs disease (TSD) disease is an autosomal recessive lysosomal storage disorder of the central nervous system (CNS), characterized by the heritable absence of the enzyme β-hexosaminidase A (HEXA), which is essential for the degradation of GM2 gangliosides." (PMID 38132111, 2023).